ALB (albumin)
Diseases named in the same sentence as ALB in open-access papers (continued):
Sharing a sentence is not in itself a finding about the gene and the disease.
chronic kidney disease (continued). "The prevalence of chronic kidney disease (CKD), defined as a persistent decrease in GFR or increase in urinary albumin excretion by more than 25%, is increasing in parallel with the duration of diabetes despite the use of therapeutic agents." (PMID 34567869, 2021). "Moreover, diabetic retinopathy with chronic kidney disease and decreased serum albumin may lower the intravascular osmotic pressure and increase hydrostatic pressure in outer retina or choroid, which could lead to fluid retention and flow into the subretinal space." (PMID 34945225, 2021). "Chronic kidney disease is defined as the existence of kidney impairment and diminished function [e.g., glomerular filtration rate (GFR) less than <60 mL/min/1.73 m2 or albumin excretion rate ≥ 30 mg/24 h] lasting greater than three months." (PMID 33401560, 2021). "Chronic kidney disease (CKD) is characterized as a reduction of glomerular filtration rate and/or increased urinary albumin excretion, and affects 10-15% of adults worldwide." (PMID 33729332, 2021). "Additionally, an increase in zinc-alpha-2-glycoprotein could be considered as a biomarker for diabetic nephropathy and an increase in albumin, clusterin, or retinol-binding protein has been identified as a possible biomarker of chronic kidney disease or acute kidney injury in humans, dogs, and cats." (PMID 32961670, 2020). "It has been shown that eGFR <60 mL/min/1.73 m2 is associated with increased risk for all-cause and cardiovascular mortality, progressive chronic kidney disease (CKD), end-stage renal disease, and acute kidney injury even with an albumin-to-creatinine ratio (ACR) <30 mg/g." (PMID 31991745, 2020). "Chronic kidney disease (CKD) is defined as a reduction in glomerular filtration rate, albumin excretion, or both." (PMID 32660587, 2020). "Chronic kidney disease (CKD) was estimated using the GFRcys, GFRcr and the urine albumin-to-creatinine ratio (UACR)." (PMID 31130557, 2020). "Glomerular filtration rate (GFR) and urinary albumin excretion rate (UAER) are used to diagnose and classify the severity of chronic kidney disease." (PMID 32985540, 2020). "We clarified the impact of the preoperative CRP/albumin ratio on AKI and evaluated the impact of postoperative AKI on end-stage renal disease (ESRD) among elderly cystectomy patients." (PMID 33193910, 2020). "Chronic kidney disease (CKD) is a complex pathology characterized by a reduced glomerular filtration rate, increased urinary albumin excretion and kidney damage." (PMID 33238586, 2020). "In chronic kidney disease, albuminuria is a recognized indicator of renal function and assessed along with GFR, and urine albumin/creatinine ratio (uACR) is recommended as a simple measure of albuminuria." (PMID 30781677, 2019). "Our group also reported previously that SGLT2i reduce the urinary albumin-creatinine ratio (ACR; mg/gCr) in Japanese T2DM patients with chronic kidney disease (CKD)." (PMID 31781668, 2019). "More recently, it has been proposed that albumin overload in PT promotes TII, and, consequently, induces progression of renal disease to end-stage renal disease." (PMID 31002704, 2019). "Chronic kidney disease (CKD), characterized by reduced glomerular filtration rate (GFR) or abnormal urinary albumin excretion, is regarded as a part of a subclinical and generalized atherothrombosis." (PMID 29435176, 2018). "Whether free S‐25(OH)D is a better measurement of vitamin D status in patients with markedly altered levels of DBP or albumin, such as chronic kidney disease (CKD) or liver failure, remains unclear." (PMID 30460340, 2018). "The percentages of a positive family history of chronic kidney disease (CKD) and alcohol consumption, as well as the urinary albumin excretion rate were similar among the different quartiles of BCAA." (PMID 30518023, 2018). "Chronic kidney disease (CKD) is characterized by reduced glomerular filtration rate, increased urinary albumin excretion, or both." (PMID 28798804, 2017).
chronic kidney disease (continued). "A 38-year-old woman, obese (219 kg), diabetic, hypertensive, chronic kidney disease (CKD) stage 4, with low plasma albumin level (2.9 g dl−1) and marked proteinuria (22 g per day) was studied." (PMID 26926587, 2016). "Chronic kidney disease (CKD) is a common chronic disease that occurs in the elderly population and presents with the characteristics of an estimated glomerular filtration rate of <60 mL/min per 1.73 m2 or a urinary albumin: creatinine ratio of >30 mg/g1." (PMID 27557856, 2016). "Over 26 million American adults have chronic kidney disease (CKD), evidenced by estimated glomerular filtration rate (eGFR) < 60 ml/min/1.73 m2 or albumin-to-creatinine ratio (ACR) ≥ 30 mg/g." (PMID 26099630, 2015). "Given the important role of EMT in the progression of CKD, albumin-induced EMT in renal tubular cells used in this study may present a useful in vitro model for EMT and chronic kidney diseases." (PMID 25832005, 2015). "The primary outcome was chronic kidney disease (CKD), defined as creatinine- or cystatin C–based estimated glomerular filtration rate (eGFRcr and eGFRcys, respectively) <60 mL/min/1.73 m2 or urine albumin-creatinine ratio (UACR) ≥3.5 mg/mmol measured at age 60-64 years." (PMID 23714172, 2013). "To address these knowledge gaps, we explored factors which influence CrCl/GFR ratio in a large diverse cohort of patients with chronic kidney disease (CKD), who had calibrated serum creatinine measurements and quantification of 24-hour urine albumin." (PMID 24305166, 2013). "Overlaps with human chronic kidney disease (CKD) and cardiovascular disease (CVD) biomarkers were observed, corresponding to proteins marking kidney damage (eg albumin, alpha-1 antitrypsin) or related to disease development (collagen)." (PMID 23236474, 2012). "Given the lack of implementation of urinary albumin:creatinine ratio for early detection, chronic kidney disease (defined as estimated glomerular filtration rate < 60 mL/min/1.73m2) was underestimated at 7.5%." (PMID 40924704, 2025). "Microalbuminuria and the albumin/creatinine ratio were more frequently elevated in P2 and P3, while estimated GFR was lower, placing a significant proportion of these patients into early chronic kidney disease stages." (PMID 41597318, 2025). "About a third of individuals with type 1 diabetes (T1DM) and almost half of those with type 2 diabetes (T2DM) may experience chronic kidney disease (CKD), which is typified by either increased urine albumin excretion or reduced renal function." (PMID 40303925, 2025). "Chronic diseases such as liver disease and chronic renal failure all have unknown impact on LDH and albumin." (PMID 38584822, 2024). "A total of 4304 adults with chronic kidney disease (estimated glomerular filtration rate (eGFR) 25–75 mL/min/1.73 m2; urinary albumin-to-creatinine ratio 200–5000 mg/g) with and without type 2 diabetes." (PMID 38097862, 2024). "Chronic kidney disease (CKD) is diagnosed when the glomerular filtration rate (GFR) is less than 60 mL/min/1.73 m2, regardless of the underlying cause, and when the albumin–creatinine ratio is ≥30 mg/g or when kidney damage is present for at least 3 months." (PMID 39202477, 2024). "Chronic kidney disease (CKD) is defined as abnormalities in kidney structure or function that persist for three months or more and have a significant impact on health, and is characterized by a decrease in estimated glomerular filtration rate (eGFR) or an increase in urinary albumin levels." (PMID 39102412, 2024). "The urinary albumin-to-creatinine ratio (UACR) is a very common marker for risk of progression of diabetic and nondiabetic chronic kidney disease (CKD)." (PMID 37174733, 2023). "Chronic kidney disease (CKD) is defined as abnormal kidney structures and function that affects health and lasts for at least 3 months, characterized by the decrease in glomerular filtration rate (GFR) and the increase in urinary albumin." (PMID 37560310, 2023).
chronic kidney disease (continued). "None of the patients had evidence of chronic kidney disease with no patients with an abnormal estimated glomerular filtration rate or an elevated albumin-to-creatinine ratio (>3 mg/mmol)." (PMID 37180518, 2023). "However, there are still no demographic studies on the effects of circulating TFA isoforms on the albumin-creatinine ratio (ACR), an early marker of chronic kidney disease." (PMID 37710270, 2023). "Forth, since serum creatinine and urinary albumin levels were not measured at baseline, it was not possible to evaluate the related information of chronic kidney disease in participants with a BP of 130–139/80–89 mmHg." (PMID 38129837, 2023). "Chronic kidney disease (CKD), defined by the presence of reduced estimated glomerular filtration rate (eGFR) and/or increased urinary albumin excretion for 3 months or more, is commonly observed amongst people with type 1 (T1DM) or type 2 diabetes mellitus (T2DM)." (PMID 37189771, 2023). "In the 2012 KDIGO classification of chronic kidney disease, CKD was divided into five grades numbered 1 through 5, with grade 3 being further divided into a and b subgrades based on eGFR and into three stages based on the degree of albuminuria calculated using the albumin/creatinine ratio." (PMID 37545695, 2023). "Chronic kidney disease (CKD) is defined by indicators of kidney damage—imaging or proteinuria (i.e., albumin to creatinine ratio)—and decreased renal function—below thresholds of glomerular filtration rate (GFR) estimated from serum creatinine concentration—for at least three months." (PMID 36496378, 2022). "Fourth, some comorbidities, such as chronic liver disease and chronic kidney disease, may have an impact on RDW and albumin levels." (PMID 36211519, 2022). "It is additionally shown that the ALB and CRE concentration results determined using the proposed method for 23 urine samples were collected from real suffering chronic kidney disease (CKD) patients are in fine agreement with those acquired operating a traditional high-reliability macroscale method." (PMID 35884299, 2022). "Only a few centres did not use eGFR (22%, n = 4) nor albumin (28%, n = 5) for chronic kidney disease screening." (PMID 36231850, 2022). "Second, the patients with chronic liver diseases, end stage renal diseases, malabsorption disease can effect serum albumin and cholesterol levels, but our data did not include these situation of the participants." (PMID 35879423, 2022). "Chronic kidney disease (CKD) is defined as the presence of kidney damage manifested by hematuria, albuminuria (albumin > 30 mg in 24 hours), or structural abnormalities, with an estimated glomerular filtration rate < 60 mL/minute/1.73 m2 persisting for more than three months." (PMID 35784967, 2022). "Besides anemia- and chronic kidney disease (CKD)-related parameters, our model found two new individual blood parameters as possible candidates to predict post-discharge death: albumin and hsTnI levels." (PMID 35743565, 2022). "We investigated the relationship between fasting serum zinc concentration and estimated glomerular filtration rate (eGFR) and albuminuria (urinary albumin-to-creatinine ratio, UACR), as well as serum zinc concentration by stage of diabetic kidney disease and chronic kidney disease." (PMID 36539708, 2022). "Earlier studies also reported that serum albumin was positively correlated with PEW indicators such as mid-arm circumference, lean body mass, and subjective global assessment score in HD patients, as in patients with chronic kidney diseases." (PMID 34984121, 2021). "Sodium-glucose cotransporter 2 inhibitor (SGLT2i) should be considered for patients with type 2 diabetes (T2D) and chronic kidney disease (CKD) having estimated glomerular filtration rate (eGFR) ≥ 30 mL/min/1.73 m2 and urine albumin-to-creatinine ratio (UACR) > 30 mg/g." (PMID 33990175, 2021).
chronic kidney disease (continued). "Chronic kidney disease (CKD) is a heterogeneous group of disorders characterized by alterations in kidney structure and function, which manifest as decreased glomerular filtration rate < 60 ml/min/1.73m2 or presence of urinary albumin excretion of ≥30 mg/day for at least 3 months." (PMID 33639878, 2021). "Patients with DM often have chronic kidney disease (CKD), so the main cause of kidney damage is considered to be GA, although a comparative analysis of glycated and oxidized albumin has not yet been made." (PMID 34638659, 2021). "In this study, the urinary albumin excretion rate in the end stage renal disease patients was not determined." (PMID 33401560, 2021). "The baseline results of laboratory tests in the studied group were within the reference ranges in most patients, with the exception of increased urine albumin, ACR, and serum creatinine, low eGFR, and low blood hemoglobin, which represent the abnormalities typical for chronic kidney disease." (PMID 34827620, 2021). "Chronic kidney disease (CKD) is defined as a glomerular filtration rate of less than 60 ml/min/1.73 m2 or increased urinary albumin excretion for no less than 3 months." (PMID 33132823, 2020). "In the present study, it was observed that a significantly increased risk of DR appeared in DM1 patients with hyperfiltration or normal glomerular filtration yet with an increased urine albumin–creatinine ratio, that is, in the G1A1/A2 stage of chronic kidney disease." (PMID 32295214, 2020). "Chronic kidney disease (CKD) is characterized by severe, irreversible kidney damage in which there is a reduction in glomerular filtration rate (GFR) <60 ml/min per 1.73 m2 or a urinary albumin-to-creatinine ratio >30 mg/g." (PMID 32879822, 2020). "In this study, we addressed the importance of the TG/HDL-C ratio for the prediction of chronic renal disease defined by both classified eGFR and classified urinary albumin-to-creatinine ratio (UACR) in non-diabetic participants." (PMID 32752179, 2020). "The following factors were significantly associated with in-hospital mortality in the unadjusted binary logistic regression analysis: SOFA score, acidosis, coagulopathy, episode of hypotension, blood lactate, albumin, creatinine, CRP value, and comorbidity with chronic kidney disease." (PMID 30423847, 2018). "Human mercaptalbumin (HMA), a reduced form of serum albumin, and non-mercaptalbumin (HNA), an oxidized form of serum albumin, are known as indicators for evaluating oxidative stress in systemic circulation, including end-stage renal disease cases." (PMID 30429539, 2018). "A recent study even added to the fact that elevated urine albumin and high CRP could increase value to MetS variables in predicting CVD and chronic kidney disease." (PMID 24835219, 2014). "Firstly, it has shown that polymorphisms within the MYH9 are associated with early changes in kidney function and urinary albumin excretion in a community based cohort as opposed to a patient population with clinically overt chronic kidney disease." (PMID 23285077, 2012). "In this study, we focused to compare the efficacy of diuretics between furosemide alone and the combination of furosemide plus albumin in stable hypoalbuminemic chronic kidney disease patients with clinical edema and without nephrotic range proteinuria." (PMID 22931630, 2012). "This study aimed to explore the relationship between the blood cell distribution width-to-albumin ratio (RAR) and in-hospital mortality in patients with congestive heart failure (CHF) combined with chronic kidney disease (CKD)." (PMID 40687564, 2025). "Although our results showed that known chronic kidney disease as a comorbidity among men and women did not appear as a significant sex difference, the difference in mean serum creatinine levels and albumin/creatinine ratio was shown to be statistically significant between the two sexes." (PMID 40731856, 2025).
chronic kidney disease (continued). "A phase 3 bardoxolone methyl evaluation in patients with chronic kidney disease and T2DM (BEACON) trial (NCT01611569) in 2185 patients with T2DM and stage 4 chronic kidney disease showed that BAR transiently increased eGFR and reduced urine albumin-to-creatinine ratio." (PMID 40534883, 2025). "Various factors contribute to the development of anemia in individuals with chronic kidney disease (CKD), including diabetic nephropathy, the stage of CKD, body mass index (BMI), smoking status, white blood cell (WBC) count, and serum albumin levels." (PMID 40655101, 2025). "The association of statin use versus no use with estimated glomerular filtration rate and urine albumin‐creatinine ratio change among participants with and without chronic kidney disease at baseline, analyzed using inverse‐probability of treatment weighting‐adjusted linear mixed‐effect models." (PMID 39696786, 2025). "In another study involving an adult population, the authors demonstrated a significant correlation between the ratio of albumin to creatinine in urine and troponin I levels in urine among patients with chronic kidney disease, but not in those without this condition." (PMID 38836067, 2024). "Diabetes and chronic kidney disease (CKD) patients comprise a distinct subpopulation of people with diabetic kidney disease (DKD), which can be recognized by amplified excretion of albumin protein in the urine or lesser glomerular filtration rate (GFR), or maybe both." (PMID 38418620, 2024). "We aimed to investigate the associations and causality between psoriasis and four renal functions, including the estimated glomerular filtration rate (eGFR), blood urea nitrogen (BUN), urine albumin to creatinine ratio (UACR), and chronic kidney disease (CKD)." (PMID 38275420, 2024). "An increase in albuminuria (urine albumin/creatinine ratio ≥ 30 mg/g) and decrease in GFR (≤ 60 ml/min/1.73 m2) are markers of chronic kidney disease (CKD)." (PMID 37479776, 2023). "Urinary albumin-to-creatinine ratio (UACR) and estimated glomerular filtration rate (eGFR) are essential for the diagnosis and staging of chronic kidney disease (CKD)." (PMID 37606804, 2023). "ABiC levels were reduced in patients with chronic renal failure, with a negative correlation observed between ABiC deterioration and the serum concentration of the uremic retention solute indoxyl sulfate—a toxin predominantly bound to albumin." (PMID 37628734, 2023). "Using different mathematical models, we compared, the albumin fraction in24-hour urine samples by electrophoresis and the APR ratio in spot samplesfrom 42 outpatients with chronic kidney disease (CKD)." (PMID 36200855, 2023). "Chronic kidney disease (CKD) is defined as a glomerular filtration rate (GFR) < 60 mL/min/1.73 m2 or kidney damage, which can be represented by an albumin-to-creatnine ratio >30 mg/g for more than 3 months." (PMID 37762501, 2023). "Chronic Kidney Disease (CKD) is defined by the presence of 1 or both of a reduced glomerular filtration rate (GFR) and an elevated urine albumin creatinine ratio (uACR) for at least a period of three months." (PMID 37624842, 2023). "The level of albumin in urine and the estimated GFR (eGFR) are two main predictors of chronic kidney disease (CKD)." (PMID 37872916, 2023). "Associations of the one-sample Mendelian randomization of urinary albumin-to-creatinine ratio (UACR), chronic kidney disease (CKD), and estimated glomerular filtration rate (eGFR) in males of the UK Biobank cohort study." (PMID 38169598, 2023). "In the Dapagliflozin in Patients with Chronic Kidney Disease (DAPA-CKD) trial, dapagliflozin was administered to CKD patients with an estimated glomerular filtration rate (eGFR) of 25 to 75 mL/min/1.73 m2 and a urinary albumin-to-creatinine ratio of 200 to 5000 mg/gCr." (PMID 37834985, 2023).